CCND1 (cyclin D1)
Diseases named in the same sentence as CCND1 in open-access papers (continued):
Sharing a sentence is not in itself a finding about the gene and the disease.
cancer (continued). "Bcl-2 and CCND1 genes, which promote cancer progression, have been reported to be important targets of miR-16." (PMID 35890348, 2022). "For 72 h, 20 μM of ISL resulted in the lowest survival number of cancer cell colonies in various esophageal squamous cancer cell lines by downregulating AP-1 and cyclin D1." (PMID 36362345, 2022). "Meanwhile, depletion of HMGB1 and ly294002 promoted apoptosis and arrested the cancer cells in G0/G1 cell cycle with the decreased expression of Cyclin D1 and CDK4 and improved P16." (PMID 36260180, 2022). "mmp1 promotes cell cycle acceleration in cancer cells by activating the cdc25a/CDK4-cyclin D1 and p21/cdc2-cyclin B1 complexes." (PMID 36225568, 2022). "This is consistent with previous studies indicating that CCND1 isoforms expression regulates cell proliferation and cell cycle progression by controlling the levels of cyclin proteins in cancer cells." (PMID 36304260, 2022). "Our early pan-cancer study also reported that patients with CCND1 amplification benefit less from ICIs." (PMID 35844619, 2022). "Multiple studies have shown that the abnormal expression of Cyclin D1 protein is the first stage in the development of a number of malignant tumors." (PMID 36072972, 2022). "According to evidence, HMGA2 promotes and accelerates cancer cell proliferation through Cyclin A, Cyclin E, Cyclin D1, Cyclin B2." (PMID 35488374, 2022). "In other words, the oncogenic cyclin D1 isoform was produced and expressed in human cancer due to alternative splicing." (PMID 35989380, 2022). "On the other hand, during G1 phase in cancer cells, PKM2 affected by PFK1, Ras, HIF-1 and PI3K/AKT/mTOR upregulates the gene CCND1 encoding cyclin D1 by increasing c-Myc expression and promoting β-catenin transactivation." (PMID 36080397, 2022). "Detailed mechanistic studies were performed that reveal that the anti-cancer effects were associated with the downregulation of the expression of VEGF, CYCLIN-D1, and STAT-3 genes and upregulation of the apoptotic Caspase-9 gene." (PMID 35216264, 2022). "Cyclin D1 is an abnormally expressed maker in cancers which promotes the G1 to S phase transition by binding to CDK4." (PMID 35224100, 2022). "Our results also showed that LLL12B downregulated the STAT3 downstream gene cyclin D1, which is involved in cancer cell proliferation." (PMID 36009550, 2022). "The cross talk between the cyclinD1-CDK4/6-pRb axis and PI3K/AKT/mTOR pathway has always been regarded as more obvious in hormonal receptor-positive and HER2-positive cancers, as ER can directly target cyclin D1 transcriptionally and activate CDK4/6-pRb." (PMID 36387174, 2022). "In cancer development, cyclin D1 can be regulated by both lncRNAs and miRNAs, which lack protein-coding capacity but affect protein synthesis and the expression of other non-coding genes to regulate cancer progression." (PMID 35287551, 2022). "CCND1, a cell cycle regulator that promotes cellular proliferation and is frequently overexpressed in human cancers, was previously identified by us and others as a central gene whose expression is upregulated in F compared with both MyoF and MyoN." (PMID 36066972, 2022). "Multiple meta-analyses suggest that cyclin D1 is the most important source of scientific evidence to study its prognostic value in human cancer." (PMID 35242498, 2022). "Both cyclin D1 and cyclin E (form G1 to S phase) play key roles in the regulation of cell cycle and are important targets for cancer cell proliferation." (PMID 35778755, 2022). "We observed that downregulation of the STAT3 target genes Bcl-xL and Cyclin D1 was correlated with mc-1Stat3 activity after treatment of 4T1 cancer cells in vitro and also of 4T1 cell-bearing mice." (PMID 35847174, 2022).
cancer (continued). "Cancer cells in primary tumors and liver metastases were highly proliferative as shown by positive staining with Ki67 and Cyclin D1 antibodies in contrast to PC sections." (PMID 35844581, 2022). "In our early research on the characterization of CCND1 amplification in pan-cancer (nine solid tumor types) using data from three databases (Geneplus, TCGA, and MSKCC) we confirmed that CCND1 amplification is associated with a poor response to ICIs." (PMID 35844619, 2022). "Ccnd1 gene expression is well documented to control cell cycle progression and control cancer development in humans and rodents." (PMID 35399296, 2022). "In cancer cells, expression of cyclin B1 was lower, but cyclin D1 was higher than in HUMEC, indicating disturbances in G2-M and G1-S transition in MCF-7 cells." (PMID 36619302, 2022). "In line with this, genes promoting cancer development and cell apoptosis (Ccnd1, Fdps, and Pik3r1) were lower expressed in M-moC than in F-moC, and MO reduced the expression in females only." (PMID 36195702, 2022). "FOXO1 regulates the expression of a number of cancer-related genes, such as p27KIP1, p21WAF1, cyclin D1, cyclin D2, FasL, p130, and Bim." (PMID 36293387, 2022). "In particular, the expression of secretion-related genes (e.g., BNDF, BRSK1, and Ccnd1) in the gastrocnemius muscle during high-intensity aerobic exercise suggests their potential role in cancer suppression." (PMID 35801156, 2022). "The changes to chromatin states and DNA accessibility at CCND1 differ subtly between the two cancer cell lines." (PMID 35863900, 2022). "Such transformation favours cancer onset and progression via the TNF-α-induced release of cytokines and angiogenic factors as well as anti-apoptotic factors such as (B-cell CLL/lymphoma 2 (BCL-2)) and cyclin D1 and cyclin E in cancer cells." (PMID 35328822, 2022). "After confirming the enhanced expression of these genes, we observed that the overexpression of FGFs/CCND1 markedly increased the cancer cell proliferation." (PMID 35814257, 2022). "ERK/c-MYC and ERK/Cyclin D1 signaling are well known in promoting proliferation and migration in cancer cells, and HTR1E has been found in human cancer cells." (PMID 35328535, 2022). "Studies have shown that cyclin D1 and c-myc are involved in the occurrence, development, and promotion of cancer." (PMID 35251170, 2022). "Increasing evidence indicates that inhibition of FOXO1 in cancer cells promoted cell cycle transition and cell proliferation by upregulation of cyclin D1." (PMID 36210843, 2022). "MiR-96-5p targets CAV1 to restrain AKT phosphorylation and its down-stream Cyclin D1 and P70 protein levels, thereby facilitating cancer cell proliferation and migration." (PMID 36017148, 2022). "Cyclin D1 is an important regulator of the cell cycle and plays a central role in cancer pathogenesis that determines uncontrolled cell proliferation." (PMID 35473552, 2022). "In a murine model of lung orthotopic cancer, knockdown of CCND1 was found to prolong survival by attenuating FGF19-induced cell proliferation." (PMID 35463335, 2022). "For example, Cyclin D1, an important regulator of cell cycle, is over-expressed with high frequency in many human cancers, targeting pathways such as the programmed cell death protein-1 (PD-1) axis." (PMID 35215436, 2022). "Cyclin D1 has been reported to be upregulated in several solid and hematologic tumors, promoting cancer progression." (PMID 36059670, 2022).
cancer (continued). "Enhanced AKT1 expression in cancer cells leads to cell proliferation and cell cycle through various downstream effectors, including cyclin D1, GSK-3, mTOR, etc.." (PMID 35646655, 2022). "Anti‐Chi3L1 antibody significantly decreased the expression of cancer growth and migration‐associated proteins, such as PCNA, cyclin D1, cyclin E, Cdk2, Cdk4, Cdk5, MMP2 and MMP9 in A549 lung metastasis model tissues." (PMID 34861103, 2022). "The amplification of FGF3/4/19/CCND1 on chromosome 11q13 was found in many cancers with TKI resistance." (PMID 35814257, 2022). "Cyclin D1 overexpression confers resistance to cisplatin- or paclitaxel-mediated apoptosis in human cancer cells." (PMID 35712514, 2022). "Amplifications at these loci have been previously associated with aggressive and drug‐resistant cancers and included several oncogenes such as MYC, CCND1, and multiple fibroblast growth factors." (PMID 35671075, 2022). "Overall, FDLE was able to strongly suppress cancer cell growth in HCT-116 cells by decreasing growth-related proteins such as cyclin D1 and CDK4 and increasing p21 through the mechanism of inhibition of NF-kB signaling pathway." (PMID 35681644, 2022). "Because cyclin D1 expression is important for the regulation of cancer cell growth, we examine the effect of Kindlin-2 ablation on mammary tumorigenesis in vivo." (PMID 35595729, 2022). "Compared to non-cancer tissues, cyclin D1 was significantly upregulated in GBM tissues (3.5-fold, data not shown), and miR-195 was significantly downregulated in GBM tissues (0.28-fold, data not shown)." (PMID 35287551, 2022). "Cyclin D1 expression is tightly regulated in normal cells but is overexpressed in various ways in cancer." (PMID 35723316, 2022). "The next candidate is cyclin D1, a protooncogene that plays a positive regulation role in cancer progression." (PMID 35723316, 2022). "A total of 20 μg/mL of DKT peritoneally injected in mice halted cancer cell proliferation by enhancing the PAK1/cyclin D1 pathway in neurofibromatosis-derived tumor cells and blocking the signal mainly enacted by protein AKT/AR." (PMID 36362345, 2022). "The overexpression of cyclin D1 contributes to uncontrolled cell proliferation and plays a central role in cancer carcinogenesis." (PMID 35723316, 2022). "The strength of the study is that we assessed the EGFR and cyclin D1 expression profile from normal cells to cancer cells and then investigated its prognostic capability in GC within the same TNM stage." (PMID 35723316, 2022). "For instance, a connection has been discovered between cell cycle arrest in the G0/G1 phase inside several cancer cells and resveratrol’s suppression of cyclin D1/CDK4." (PMID 36160435, 2022). "The oncogenic roles of the CCND1 have been displayed in many human cancers, including thyroid, hepatocellular, colon, and prostate cancers." (PMID 35246017, 2022). "For example, the checklist published by King and Lam (2019) would suggest DLBCL, NOS as an appropriate diagnosis for our patient, given that his cancer was a cyclin-D1-, CD10+, BCL6-, lymphoid, large B-cell lesion with a high labeling of Ki-67." (PMID 36158446, 2022). "In particular, RTKs promote cancer cell proliferation, increasing c-Myc and cyclin D1 oncogenes expression." (PMID 35057104, 2022). "From 10 distinct DHSs within CCND1, five are common to both cancer cell lines, three are specific to Z-138, and two are specific to U266." (PMID 35863900, 2022). "CREPT potentiated Wnt-mediated signaling by interacting with TCF4 and β-catenin, which led to higher expression of cyclin D1 to support cancer cell proliferation." (PMID 36313570, 2022). "CCND1 is a main regulator of the cell cycle, and has been reported to be involved in the cell proliferation of various cancers." (PMID 36612120, 2022). "Aberrant expression of cyclin D1 and cyclin E2 has been reported in various human cancers and correlates with the clinical outcome." (PMID 36012128, 2022).
cancer (continued). "CCND1 is a well-recognized human oncogene, and it plays a critical role in therapeutic resistance in many cancers." (PMID 35814257, 2022). "Expression of Cyclin D1 increased along with progression from low-grade (median—10%), through high-grade dysplasia (15%) to carcinoma (30%) (p = 0.01)." (PMID 35626215, 2022). "Our results showed that expression of Cyclin D1 increased on progression along with the lesion—from dysplasia (10–15%) to carcinoma (30%)." (PMID 35626215, 2022). "We also checked the expression of Cyclin D1, which is an important regulator of cell cycle, with many carcinomas being characterized by Cyclin D1 overexpression that induces uncontrolled cell proliferation." (PMID 35720292, 2022). "High CCND1 CN was seen among all histopathological subtypes except tubular and metaplastic carcinomas." (PMID 35459982, 2022). "Western blot analysis also showed that knockdown of POLE2 inhibited the expression levels of cancer-related pathway proteins including p-Akt, CCND1, and PIK3CA, while the expression of MAPK9 was promoted." (PMID 33644060, 2021). "Cyclin D1 is a regulator of cell cycle progression, controls cell proliferation, and is highly expressed in various human cancers including CRC." (PMID 34737955, 2021). "We also found significant enrichment for known cancer driver genes from the COSMIC (Catalogue Of Somatic Mutations In Cancer) database in our predicted causal genes list, such as CDK4, EGFR, PTK6, and CCND1 (29/264; Fisher adjusted p < 0.01)." (PMID 34010657, 2021). "The transcriptional activation of β-catenin downstream targets, including MMP-9, Myc, Axin2, and cyclin D1, is able to promote cell cycle progression, cell proliferation, and metastasis in the progression of cancer." (PMID 34545072, 2021). "F. nucleatum has also been shown to upregulate the Toll-like receptor (TLR) signaling and activation, of cell cycle regulators STAT3 and cyclin D1, leading to the growth of cancer cells." (PMID 34299675, 2021). "For example, in various human cancers STAT3 induces genes that permit sustained proliferation, such as those encoding cyclin D1 (CCND1) and telomerase (TERT)." (PMID 34809691, 2021). "Some studies suggested that NF-κB is involved in cancer progression; conventional explanations for this phenomenon include the induction of the expression of proto-oncogenes such as c-myc and cyclin D1, adhesion molecules such as VEGFs and MMPs, and miRNAs." (PMID 34163032, 2021). "Only the CCND1-CDK4 and CDK6 complex has raised interest as a possible actionable target, whereas, in contrast, despite its prognostic relevance in cancer, the regulatory member CCND1 per se has received less attention." (PMID 34445095, 2021). "From the remaining five, only the roles of MYC and CCND1 as inducers of cell proliferation and cancer progression in connection with YAP were very well established." (PMID 33514403, 2021). "Curcumin causes the suppression of NF-κB (a transcription factor whose constitutive expression is implicated in many cancers), leading to a decrease in its target genes such as COX-2 and cyclin D1 and ultimately leading to apoptosis." (PMID 34164422, 2021). "A recently published integrative analysis from the “Pan-Cancer Analysis of Whole Genomes” of the Consortium of the International Cancer Genome Consortium (ICGC) reported chromothripsis involving CCND1 on chromosome 11." (PMID 33804108, 2021). "It was suggested that complex events involved with CTs in the formation of derivative chromosomes contributed to the amplification of cancer-related genes, such as CCND1, CDK4, MDM2 and ERBB219." (PMID 33927198, 2021). "In 786-O-SR cells, treatment with KTZ alone inhibited the growth of cancer cells through inhibition of cyclin D1 protein expression, and the combination of sunitinib and KTZ increased the anticancer effect." (PMID 33986386, 2021).
cancer (continued). "Having shown that TGFβ inhibits BMP4 while promotes stemness, we next assessed the role and contribution of cyclin D1 in controlling cancer stem cell numbers." (PMID 33649296, 2021). "Cyclin D1 is another regulator that drives G1 to S phase progression and its dysregulation can be frequently found in human cancers including HCC." (PMID 34583719, 2021). "CDK4/6 inhibitors are being used for many clinical trials and the efficacy has been assessed in many types of cancers where cyclin D1 is overexpressed." (PMID 33122824, 2021). "PARP, Bcl-2, and cyclin D1 present essential functions in the apoptosis and cell cycle and have always been observed with high expressions in various cancers." (PMID 34239588, 2021). "It has been reported that the abnormal levels of CDK4, CDK6, and cyclin D1 in various human cancer cells are closely related to the abnormal proliferation of cancer cells." (PMID 34574146, 2021). "Correspondingly, up-regulated CCND1 and suppressed cancer aggressiveness were observed after METTL3 RNAi." (PMID 34178650, 2021). "It has already been shown that γ-tocopherol inhibits cell cycle progression and cyclin D1 expression in human cancer cells." (PMID 33920203, 2021). "Some cancer-related factors including Akt, p-Akt, CCND1, CDK6, and PIK3CA were detected by the western blot." (PMID 33996561, 2021). "In fact, the cyclin D1 oncogene is highly expressed in many cancers and, despite its proliferation-activating properties, it has been linked to a less malignant phenotype." (PMID 34071030, 2021). "Excepting the dominant-negative regulator of STAT3α, STAT3β can repress the expression of Bcl-xL, p21, cyclin D1, and cyclin C, inducing apoptosis and cell cycle arrest in cancer cells." (PMID 33670049, 2021). "This suggests the potential of NSC765600 and NSC765691 compounds to inhibit CCND1/CDK4/PLK1/CD44 expressions in cancer." (PMID 34063946, 2021). "For example, in different cancer types the let-7 miRNA family alone modulates the abundance of CCND1, CDK4 as well as MYC." (PMID 33748099, 2021). "Cyclin D1 protein expression was reduced and correlated with pS6(Ser235/236) downregulation in 5 of 7 cancer cell lines treated with JHU-083." (PMID 33681764, 2021). "miR-922 targets and inhibits CYLD expression, leading to promotion of c-Myc and cyclin D1 as well as cancer cell proliferation, thus presenting another possible mechanism for HCC promotion." (PMID 33952719, 2021). "We further extended our analysis on other members of RB1 pathway, including CDKN2A (p16Ink4a), CCND1, CDK4, and CDK6, which are often mutated in different cancers." (PMID 33591981, 2021). "Cell cycle analysis and downregulation of cyclin D1 indicated cancer cell cessation in the G0/G1 phase." (PMID 33900505, 2021). "These excess β-catenin translocated to the nucleus and activated the downstream genes expression, including c-Myc, Sox2, Nanog, Oct4, Survivin and Cyclin D1, thus contributing to oncogenesis and cancer development." (PMID 34257574, 2021). "The genes selected included epithelial (KRT5, CDH1, EpCAM), mensenchymal (VIM, SNAI1, TWIST), stem (ALDH1A1, PROM1), breast specific (ESR1, PALB2) and other genes related to cell cycle or other cancer pathways (CCND1, CTNNB1, Ki67, etc.)." (PMID 34071445, 2021). "This gene is aberrantly highly expressed in many malignant tumors, and patients with high expression of CCND1 gene have a higher degree of malignancy and worse prognosis." (PMID 34806539, 2021). "Some target genes, such as MMP9 and cyclin D1, are involved in oncogenesis, regulating cancer proliferation and metastasis." (PMID 33407510, 2021). "In normal cells, CCND1 has a very short life due to UPS degradation whereas in cancer cells, inhibition of turnover and increased levels of CCND1 were shown." (PMID 34445095, 2021). "One study has reported the role of p21 in potentiating cancer stem cells (CSC) via the activation of canonical Wnt signaling due to TCF1/Cyclin D1 upregulation." (PMID 33514407, 2021).